CTLA4 (cytotoxic T-lymphocyte associated protein 4)
Diseases named in the same sentence as CTLA4 in open-access papers (continued):
Sharing a sentence is not in itself a finding about the gene and the disease.
melanoma (continued). "Most reports on the combination of RT and ICIs refer to patients with malignant melanoma treated with ipilimumab targeting the CTLA4 checkpoint, since it was approved for the treatment of metastatic melanoma in 2011." (PMID 31156434, 2019). "Proof that this was also the case in humans came in 2003 in a clinical investigation, where CTLA-4 blockade increased tumor immunity in some previously vaccinated melanoma and ovarian carcinoma patients." (PMID 31134056, 2019). "Small case studies have shown that patients with mucosal melanoma of the lower genital tract respond favorably to the combined treatment of a CTLA-4 antibody and radiation therapy." (PMID 31533363, 2019). "Anti-CTLA-4 humanized antibodies, as ipilimumab, were the first to show therapeutic efficacy against melanoma." (PMID 30792754, 2019). "To test this, we first investigated the expression levels of CTLA-4, PD-1, and PD-L1 on melanoma cells." (PMID 31192129, 2019). "First, the expression of ER stress markers was assessed in murine melanomas collected following treatment with isotype or anti-CTLA4 antibodies." (PMID 30940817, 2019). "ICOS potentiates anti-tumor immunity mediated by CTLA-4 blockade in murine models of prostate cancer and melanoma." (PMID 30788290, 2019). "A combination of anti-CTLA-4 and anti-PD-1 targeting antibodies are now commonly used to treat unresectable and/or advanced melanoma with great success and an overall median survival rate that has not yet been reached." (PMID 31771150, 2019). "Here, we present an immunological evaluation of CTLA-4 haploinsufficient, LRBA deficient, and ipilimumab-treated melanoma patients, focusing on the degree of CTLA-4 disruption in each patient category." (PMID 31156616, 2019). "Conversely, some studies associated soluble PD-L1 levels in patient plasma with better response to immune checkpoint inhibitors, particularly to anti–PD-1 (aPD-1) and anti–CTLA-4 antibodies in patients with melanoma or multiple myeloma." (PMID 30872362, 2019). "Ipilimumab, the only FDA approved anti-CTLA-4 monoclonal antibody for treatment of melanoma was and is still being evaluated in several phase I, II, and III clinical trials for patients with PCa as a single agent or combination therapy." (PMID 31572678, 2019). "The remarkable advances in melanoma immunotherapy occasioned by the development of CTLA-4 and PD-1/PDL1 checkpoint inhibition underscores the importance of understanding potential contributions of melanoma-elaborated cytokines such as IL32." (PMID 30953519, 2019). "The introduction of BRAF/MEK inhibitors as well as checkpoint inhibitors with anti-CTLA-4 and anti-PD-1 antibodies has offered new hope for patients with stage 4 melanoma." (PMID 30617871, 2019). "The findings are validated to some extent in a separate study, wherein memory subsets were predictive of response to CTLA-4 blockade in patients with melanoma." (PMID 31775882, 2019). "Ipilimumab, a humanized monoclonal antibody against CTLA-4, has been applied as a biopharmaceutical for treating melanoma in humans." (PMID 31665022, 2019). "Immune checkpoint inhibitors revolutionized the treatment of several cancer types, including melanoma, and immune checkpoint blockade with anti-PD-1 and anti-CTLA-4 antibodies is becoming a frontline therapy in metastatic melanoma." (PMID 31824260, 2019). "In a phase I clinical trial, MART-1 peptide-pulsed DCs combined with tremelimumab (anti-CTLA-4) resulted in objective and durable tumor responses in melanoma patients." (PMID 30923527, 2019). "PD-1 blockade has led to improved survival and lower rates of high-grade toxicities in advanced melanoma compared to CTLA-4 blockade." (PMID 30682108, 2019). "The impact of preventing CTLA-4-mediated suppression has become evident in melanoma patients where the blocking of this checkpoint has improved treatment success and life expectancy." (PMID 31333674, 2019).
melanoma (continued). "The first such trial evaluated single-agent anti-CTLA-4 ipilimumab (10 mg/kg given every 3 weeks for four doses, followed by 10 mg/kg every 12 weeks) in melanoma BM patients (NCT00623766)." (PMID 30854898, 2019). "Others have shown that EZH2 inactivation can potentially synergize with checkpoint-based immunotherapy including anti-CTLA4 and PD-L1 in preclinical models of melanoma and ovarian cancer." (PMID 30692641, 2019). "A number of case studies of HIV-1-infected individuals with NSCLC or malignant melanoma who were treated with nivolumab or ipilimumab (anti-CTLA4) reported changes in HIV-1 RNA or DNA." (PMID 30682108, 2019). "After the first indication of melanoma, an increasing list of additional cancer types are now treated with immune system targeting antibodies to PD-1, PD-L1 and CTLA-4, alleviating inhibition signals on T cells." (PMID 31623687, 2019). "Other circulating immune cells, such as immunosuppressive MDSCs, have been shown to correlate with poor response to anti-CTLA-4 therapy in multiple studies in melanoma patients." (PMID 31816940, 2019). "The role of the immune system in melanoma is widely known and immunotherapies based on immune checkpoint (CTLA4 and PD1) inhibitors have been developed, such as anti‐CTLA4 and anti‐PD1." (PMID 30499222, 2019). "A study in preclinical melanoma models (BRAFV600EPTEN−/−) has shown synergy combining TGF-β receptor kinase inhibitor I with anti-CTLA-4 antibodies." (PMID 30853982, 2019). "The bulk CD4+ CTLs in our cultures included large numbers of naïve T cells, whose cytolytic activity potential was significantly enhanced after CTLA-4 blockade with checkpoint inhibitors in a mouse model of combined immunotherapy for melanoma." (PMID 30783516, 2019). "In this prospective biomarker study, we included 35 melanoma patients with ipilimumab (anti-CTLA-4) and nivolumab (anti-PD-1) therapy." (PMID 31300034, 2019). "In this regard, the manipulation of CTLA-4 signaling (e.g., by using Ipilimumab) has been investigated in clinical trials and approved for treatment of advanced melanoma." (PMID 31440243, 2019). "In a Phase 2 trail, CTLA-4 inhibitor ipilimumab demonstrated activity in brain metastasis in patients with melanoma." (PMID 31570099, 2019). "As research into therapies utilizing CTLA-4 and PD-1/PD-L1 blockade to treat melanoma has advanced, further targets have been sought out in an effort to overcome issues such as incomplete tumor regression or relapse following treatment." (PMID 30941125, 2019). "First, in the setting of advanced melanoma, the development of irAEs in patients treated with CTLA4 inhibitors proved to be significantly correlated with higher tumor response rate and probability of survival." (PMID 30944023, 2019). "In melanoma patients treated with bacillus Calmette-Guerin (BCG) followed by CTLA4 blockade, increase in tumor autoantibody repertoire precedes high grade irAEs." (PMID 31086070, 2019). "Immune checkpoint inhibitors such as Ipilimumab, a CTLA-4 inhibitor for the treatment of melanoma, is already approved by the FDA." (PMID 30819254, 2019). "In order to assess the potential in combining oncolytic virotherapy with immune checkpoint inhibition, melanoma cell lines Sk29Mel-1 and Mz7Mel were first analyzed for expression of the immune checkpoint proteins CTLA-4, PD-1, and PD-L1." (PMID 31192129, 2019). "Both checkpoint inhibitors block the interaction of PD-1 and CTLA-4 on melanoma cells with their counterparts on the surface of DCs." (PMID 31192129, 2019). "Treatment with a combination of PD-1 and CTLA-4 targeted checkpoint inhibition has improved outcome of melanoma patients and led to durable remissions but is also associated with significant toxicities." (PMID 30791949, 2019). "In these patients, the T cell- mediated anti-tumor response against melanoma, and ovarian carcinoma was increased after the administration of an anti-CTLA-4 antibody." (PMID 31164886, 2019).
melanoma (continued). "The first systemic treatment ever to significantly improve OS for patients with unresectable advanced melanoma was the CTLA-4 blocking monoclonal antibody (mAb) ipilimumab." (PMID 31182961, 2019). "The anti-CTLA-4 antibody ipilimumab was the first immune-checkpoint antibody approved for the treatment of patients with advanced melanoma due to its survival benefit compared to standard chemotherapy." (PMID 30700842, 2019). "The second study involved patients with advanced melanoma (n = 74), ten of whom received antibiotics within 30 days of administration of anti-PD-1- and/or anti-CTLA-4 MAb-targeted therapies." (PMID 31616428, 2019). "For instance, a GM-CSF-producing tumor cell vaccine combined with CTLA-4 blockade has important synergistic effects in reducing tumor size and increasing the antitumor immune response in a melanoma model and in a prostate cancer model." (PMID 30923527, 2019). "For example, cytotoxic T lymphocyte associated antigen 4 (CTLA4), programmed death-1 (PD-1), and programmed death ligand-1 (PD-L1) inhibitors were found to have promising antitumor effects on malignant melanoma and non-small-cell lung carcinoma." (PMID 31998650, 2019). "Together, degrees of repertoire restrictions in CD4+ and CD8+ blood T cells showed positive correlations with each other in melanoma patients both before and after CTLA4 blockade." (PMID 31275310, 2019). "The development of these immunotherapy agents has increased since the first approval of anti-CTLA-4 therapy (ipilimumab) by the United States Food and Drug Administration for melanoma in 20112." (PMID 30622243, 2019). "Monoclonal antibodies to CTLA-4 and PD-1 are now in clinical use for melanoma and NSCLC, and they are currently undergoing further assessment for the treatment of other cancers." (PMID 30975211, 2019). "In melanoma, it has also been reported that single treatment with anti-CTLA4 or anti-PD-1 antibodies yielded modest clinical benefit." (PMID 31540045, 2019). "Several checkpoint inhibitors, e.g., Ipilimumab (a CTLA4-i), Nivolumab and Pembrolizumab (PD-1-i), have been approved to treat melanoma and lung cancer, with demonstrated improved survival." (PMID 31795835, 2019). "CTLA-4-neutralizing antibodies are now approved for the treatment of advanced melanoma, and are in development for treating other cancers as well." (PMID 31061392, 2019). "Combination of anti-CTLA-4 with TGF-β receptor kinase inhibitor in melanoma murine model showed synergistic activity with an increase in the CD8+/Treg ratio." (PMID 35582715, 2019). "In advanced melanoma the combination of nivolumab (anti-PD-1) and ipilimumab (anti-CTLA-4) resulted in a response rate of 53% and had a manageable safety profile similar to respective single antibody administrations." (PMID 31291357, 2019). "Since patients who were treated with anti-CTLA-4 therapy were included in the TCGA melanoma dataset, we performed the Kaplan-Meier (KM) survival analysis by excluding them separately and found similar result." (PMID 31729408, 2019). "CTLA-4 has become an immunotherapy target whereby its blockade with a monoclonal antibody has resulted in improved survival in advanced melanoma patients, amongst other malignancies." (PMID 31156616, 2019). "For the first time, the relationship between the occurrence of specific bacterial species in gut microbiome and the effectiveness of anti-CTLA-4 or anti-PD-1/PD-L1 antibodies have been observed in melanoma patients." (PMID 31003463, 2019). "The first, rs231779 on chromosome 2, is an eQTL for CTLA4, which is a target for immunotherapy medications including ipilimumab and tremelimumab, which are already in use for melanoma." (PMID 31174203, 2019). "Although toxicity profiles especially those associated with CTLA-4 blockade use may be an important concern in combined therapies, pre-clinical and clinical findings into the efficacy of combining checkpoint blockade antibodies showed encouraging results in melanoma." (PMID 30941125, 2019).
melanoma (continued). "Immunomodulatory drugs, such as PD-1/PD-L1 or CTLA-4 inhibitors, have a great therapeutic potential in metastatic melanoma, including melanoma brain metastases." (PMID 32309611, 2019). "Although now tested only in melanoma, dual blockade of PD-1 (with nivolumab) and CTLA-4 (with ipilimumab) resulted in higher response rate and longer survival than in patients treated with a single IC inhibitor." (PMID 31581738, 2019). "Clinical trials in melanoma brain metastases with combined PD-1/CTLA-4 blockade showed ~50% intracranial response rate." (PMID 31481958, 2019). "Ipilimumab (antibodies targeting CTLA4) are currently in use to treat melanoma patients with stage III or IV disease." (PMID 31174203, 2019). "Both anti-PD-1 and anti-CTLA-4 immunotherapies are administered intravenously (i.v.)and have been shown to induce anti-tumor responses in patients with cancers, including melanoma, non-small cell lung cancer, and renal cell carcinomas." (PMID 31754400, 2019). "Mice vaccinated with irradiated B16 melanoma cells and treated with checkpoint signal blockade including anti-CTLA-4 and/or anti-PD-1resulted in marked resolution of solid tumor burden and increased CD4+/CD8+ to Treg ratio in the tumor." (PMID 31681327, 2019). "Recently, two studies noted the crucial role of the interferon (IFN) pathway in melanoma patients who become resistant to either PD-1 or CTLA-4 antibody therapy." (PMID 31110180, 2019). "The breakthrough for immunotherapy in oncology started with the approval of the anti-CTLA-4 monoclonal antibody ipilimumab for second-line treatment of advanced melanoma in 2011, and the following extension to first-line therapy in 2013." (PMID 31092853, 2019). "Anti-CTLA-4 antibody therapy is only approved for melanoma and renal cell carcinoma; however, there are multiple ongoing clinical trials with anti-CTLA-4 as one of the combination agents." (PMID 31572678, 2019). "Clinical trials highlighting combination therapy of CTLA-4 and PD-1 or PD-L1 blockade demonstrated superior clinical efficacy to monotherapy in human melanoma." (PMID 31681327, 2019). "We describe two patients with metastatic melanoma who initially showed a durable partial response to either a melanoma-peptide/interleukin-12 vaccine or combined anti-CTLA-4 + anti-PD-1 therapy, but subsequently developed new treatment-resistant metastases." (PMID 31703593, 2019). "Combination of anti-PD-1 with anti-CTLA-4 therapies significantly induced tumor regression in various cancer types, including melanoma." (PMID 31134073, 2019). "A contribution of the immune regulation/checkpoint pathway was surprisingly absent, given our knowledge that immunosuppression increases nevus count quite promptly and the recent success of CTLA4 inhibitors in the treatment of melanoma." (PMID 30429480, 2018). "CPI therapy targeting CTLA-4 and PD-1 has improved clinical outcomes in patients with BM, including objective responses in patients (pts) with active, untreated melanoma or non-small cell lung cancer (NSCLC) BM." (PMID 30400822, 2018). "For example, combination of anti-PD-1 and anti-CTLA4 drugs has demonstrated additive efficacy in melanomas, non-small-cell lung cancer and renal cell carcinoma." (PMID 30514251, 2018). "The presence of soluble CD25 (the α-chain receptor of interleukin-2; IL-2) in pre-treatment serum of melanoma patients undergoing anti-CTLA-4 mAb therapeutic regimen has been shown to be an independent indicator of OS." (PMID 30004433, 2018). "Circulating T cells with specific reactivity against TAAs, such as MART-1 and NY-ESO-1, have been observed in melanoma patients administered with CTLA-4 blocking agents." (PMID 30004433, 2018). "Since the approval of anti-CTLA4 therapy (ipilimumab) for late-stage melanoma in 2011, the development of anticancer immunotherapy agents has thrived." (PMID 29556198, 2018).
melanoma (continued). "Recently, Mo et al43 reported that IFNγ induced melanocyte and melanoma cells to express human CTLA‐4 gene, which was dependent on IFNGR/STAT1 signaling pathways." (PMID 30039553, 2018). "With CTLA-4 blockade by Ipilimumab or PD-1 inhibition with Nivolumab, response rates of 30-40% were observed in melanoma patients as monotherapies and combination therapy achieved a response rate of over 50%." (PMID 29970158, 2018). "Immune checkpoint inhibitors (anti-PD-1 and anti-CTLA-4 antibodies) are a standard of care for advanced melanoma." (PMID 29610684, 2018). "We previously reported the results of a phase II study of the combination of IFNα-2b and the anti-CTLA4 antibody tremelimumab in patients with advanced inoperable melanoma." (PMID 30352626, 2018). "In 2010, a randomized phase III trial reported remarkable response to Ipilimumab, mAb against CTLA-4, in melanoma patients." (PMID 29970158, 2018). "The in vivo effect of a-CTLA4-TGFβRII on Tregs was examined in human melanoma tumor-bearing NSG mice (NOD/Shi-scid IL-2rgnull) that were immune reconstituted with tumor-matched human leukocyte antigen (HLA) A2 + human CD34+ bone marrow (BM) cells." (PMID 29467463, 2018). "In melanoma, microbiota composition can predict resistance to immunotherapy-induced colitis and peculiar microbiota species can condition or potentialize CTLA4 or PD-L1 therapy effects." (PMID 29615661, 2018). "We used mass cytometry (CyTOF) to comprehensively profile peripheral blood of melanoma patients, in order to find predictive biomarkers of response to anti-CTLA-4 or anti-PD-1 therapy." (PMID 29510697, 2018). "Remarkably, therapeutic melanoma trials with checkpoint inhibitors directed to CTLA-4 or PD-1 that prospectively stratify patients for age to assess for differences in outcome report that the response is independent of age." (PMID 29546435, 2018). "For this we utilized anti murine-CTLA4 mAb 9D9 which has been tested previously in the B16F10 murine melanoma model." (PMID 29615812, 2018). "Checkpoint inhibitors nivolumab, an anti-programmed death-1 (PD-1) antibody, and ipilimumab, an anti-cytotoxic T-lymphocyte-associated protein 4 (CTLA-4) antibody, demonstrated increased survival in untreated melanoma and were FDA approved in 2015." (PMID 30568917, 2018). "A combination of CTLA-4 inhibitors and anti-PD-1 agents has been shown to prolong overall survival in patients with advanced melanoma." (PMID 30537980, 2018). "The reported melanoma in a CTLA-4-insufficient patient (CZ.II.2) is alerting and beyond our present understanding of the functional interaction between immune checkpoints and melanoma development." (PMID 30250467, 2018). "We determined if CD4+ T cells of young and old melanoma patients show increased expression of the checkpoint molecules PD-1 and CTLA-4." (PMID 29546435, 2018). "Co-administration of PD-1 and CTLA-4 antibodies to patients with melanoma was shown to increase therapeutic efficacy, whereas adverse events were only moderately increased as compared to CTLA-4 blockade alone." (PMID 30233564, 2018). "CTLA‐4 is one of immune checkpoint molecules expressed on T cells and CTLA‐4 inhibitor is dramatically effective at restoring T‐cell responses in the patients with melanoma." (PMID 30039553, 2018). "In an analogous scenario, the impact of PD-L1 expression is abated in patients with melanoma treated with PD-1 plus CTLA-4 blockade, and in a report of 17 patients with melanoma treated with combination immunotherapy, TMB did not correlate with response." (PMID 29657128, 2018). "CTLA-4 and PD-L2 genes were expressed at higher levels in the pretreatment melanoma tumors of patients who derived benefit from CTLA-4 antibodies." (PMID 29970158, 2018).